MIR4733 (microRNA 4733)
Synonyms: hsa-mir-4733
Gene: MicroRNA gene on chromosome 17 (31,094,350 to 31,094,425, reverse strand). Ensembl gene ENSG00000265444.
Homologues: Orthologues: chimpanzee MIR4733 (100% identical).